TUFT1 (tuftelin 1)
Diseases named in the same sentence as TUFT1 in open-access papers (continued):
Sharing a sentence is not in itself a finding about the gene and the disease.
cancer (14 papers, 2017 to 2025). A tumor composed of atypical neoplastic, often pleomorphic cells that invade other tissues. "The present study identified TUFT1 as a factor associated with poor prognosis in several types of cancers." (PMID 29423269, 2018). "Therefore, TUFT1 is a potential target for diagnostic and therapeutic approaches for cancers." (PMID 41022752, 2025). "Thus, TUFT1 represents a promising target for diagnostic and therapeutic approaches for cancers." (PMID 41022752, 2025). "TUFT1 is highly expressed in several cancers, such as thyroid, hepatocellular, pancreatic, breast, and stomach carcinomas and predicts worse clinical status and poor prognosis." (PMID 41022752, 2025). "Tuftelin1 (TUFT1) is an acidic protein component of developing and mineralizing tooth tissue that is related to oncogenesis of cancers." (PMID 36797791, 2023). "One universal concept that has emerged from previous studies is that TUFT1 promotes cancer development and progression through different signaling pathways." (PMID 36139487, 2022). "Recent studies have shown that TUFT1 promotes proliferation, metastasis, and epithelial–mesenchymal transformation of cancer cells through the Ca2+/PI3K/AKT pathway." (PMID 35205261, 2022). "Most studies about TUFT1 focused on calcification and mineralization of teeth, while its role in cancers has gained attention in recent years." (PMID 35769513, 2022). "TUFT1 elevation in RCC can promote cancer cell proliferation, migration and EMT progression, via the PI3K/AKT signaling pathway." (PMID 34257606, 2021). "Tuftelin 1 (TUFT1), a protein functioning distinctively in different tissues, is reported to be elevated in several types of cancers and the elevation of TUFT1 is correlated with unfavorable clinicopathologic characteristics and poor survival." (PMID 34257606, 2021). "Increased expression of TUFT1 can promote the growth and metastasis of cancer cells through distinctive pathways in different cancers." (PMID 34257606, 2021). "In conclusion, LINC01123 was overexpressed in HCC and accelerated cancer cell proliferation and invasion by regulating the miR-34a-5p/TUFT1 axis." (PMID 32760198, 2020). "Among 28 human cancers, 11 cases showed elevated TUFT1 levels, while 17 cases showed decreased SHMT1 levels, compared with the corresponding normal tissues." (PMID 30755243, 2019). "TUFT1 is therefore considered to be involved in cancer, but its physiological functions in normal and cancerous tissues remain uncharacterized." (PMID 29423269, 2018). "Immunohistochemistry (IHC) analyses showed that TUFT1 positivity rate was 63.0% (92/146) in the cancer tissue samples, which was significantly higher than that observed in the adjacent normal breast tissues (16.7%; 10/60 samples)(P= 0.000)." (PMID 29088838, 2017). "This may be because cell proliferation generally precedes genetic variations in these cancers, which require the dephosphorylation of TUFT1." (PMID 41022752, 2025). "Thus, TUFT1 is a crucial module that balances cell proliferation and genetic variation in cancer cells." (PMID 41022752, 2025). "TUFT1 is an acidic phosphorylated glycoprotein that is frequently overexpressed in human cancers." (PMID 35769513, 2022). "It is warranted to determine whether TUFT1 mRNA and/or protein level could be used as a biomarker for cancer diagnosis or stage classification." (PMID 34257606, 2021). "In addition, we compared the sensitivity of A549 (high expression of TUFT1) and NCI-H460 (low expression of TUFT1) cancer cells to perifosine in terms of the distribution of mTORC1 and lysosomes." (PMID 29423269, 2018). "The role of these genes has been reported in cancers, however, networks constructed between TUFT1 and genes had shown that TUFT1 did not associate with these genes except RelA." (PMID 29088838, 2017). "Thus, further research may position TUFT1 as a biomarker or as a therapeutic target for various cancers." (PMID 29423269, 2018).
cancer (continued). "The upregulation of mRNA expression of several oncogenes, including FOSL2, TUFT1, HMGA1, and HDGF, most often leads to the acquisition of cisplatin resistance, while increasing the proliferation of cancer cells and reducing their apoptosis." (PMID 36139487, 2022). "Our previous study demonstrated that TUFT1 was overexpressed in HCC and promoted the proliferation, migration, invasion, and EMT of cancer cells by activating the AKT pathway." (PMID 32908135, 2020). "TUFT1 expression was previously reported to be elevated in HCC cancer tissue (CT) comparing to adjacent noncancerous tissue (NT)." (PMID 34257606, 2021). "The acidic protein tuftelin 1 (TUFT1) is involved in mTORC1 activation by interacting with the RAB GTPase activating protein 1 (RABGAP1) and therefore may constitute a biomarker or a candidate for targeted therapy in mTOR activated, progressive cancers." (PMID 31261735, 2019).
infection (1 paper, 2017). The state of being infected such as from the introduction of a foreign agent such as serum, vaccine, antigenic substance or organism. "Initially, TUFT1 expression was inhibited by the infection of 293T cells with TUFT1-small interfering RNA (siRNA)-carrying lentiviral particles (TUFT1-knockdown group), or scrambled (scr)-siRNA-carrying lentiviruses, as a control." (PMID 29088838, 2017).
TUFT1 also shares sentences with these, for which no sentence is quoted: osteosarcoma (2 papers); cognitive decline (1); colon cancer (1); pneumococcal infection (1); stomach adenocarcinoma (1); thyroid carcinoma (1).